KRT33B (keratin 33B)
Synonyms: K33B; HHA3-II; KRTHA3B; Ha-3II; HA3II; KRTHA3A
Tractability: No criterion of Open Targets' tractability assessment is met for any kind of drug.
Gene: Protein-coding gene on chromosome 17 (41,363,498 to 41,369,813, reverse strand). Ensembl gene ENSG00000131738.
Subcellular location (Human Protein Atlas): Cytosol; End piece; Principal piece; Equatorial segment; Mid piece
Pathways (Reactome):
Developmental Biology: Formation of the cornified envelope; Keratinization
Gene Ontology:
Molecular function: protein binding; structural constituent of skin epidermis; structural molecule activity
Biological process: hair cycle; epithelial cell differentiation; intermediate filament organization; morphogenesis of an epithelium
Cellular component: extracellular exosome; extracellular region; cytoskeleton; cytosol; keratin filament
Genetic constraint (gnomAD): Loss-of-function variants: 36 observed, 44.21 expected, observed/expected ratio (o/e) 0.81, 90% interval 0.62 to 1.08. The upper end of that interval is the gene's LOEUF score, 1.08, which puts it in group 4 of 6, group 1 being the genes least tolerant of losing a copy. Missense variants: 516 observed, 520.64 expected, observed/expected ratio (o/e) 0.99, 90% interval 0.92 to 1.07. Synonymous variants: 232 observed, 221.35 expected, observed/expected ratio (o/e) 1.05, 90% interval 0.94 to 1.17.
Homologues: Orthologues: chimpanzee KRT33B (99% identical), macaque KRT33B (97% identical). Paralogues in human: KRT31 (94% identical), KRT33A (94% identical), KRT34 (87% identical), KRT36 (69% identical), KRT35 (69% identical), KRT32 (67% identical), KRT38 (60% identical), KRT39 (59% identical), KRT37 (59% identical), KRT40 (59% identical), KRT14 (50% identical), KRT16 (49% identical), and 56 more.
Diseases named in the same sentence as KRT33B in open-access papers:
KRT33B is named in the same sentence as 5 diseases in open-access papers, as found by Europe PMC text mining. Sharing a sentence is not in itself a finding about the gene and the disease. The quoted sentences say what the papers report.
glioma (1 paper, 2022). A benign or malignant brain and spinal cord tumor that arises from glial cells (astrocytes, oligodendrocytes, ependymal cells). "Recent analyses also highlight that some keratin forms (KRT33B, KRT75) can be used as prognostic biomarkers for early detection of low-grade gliomas, and others (KRT75) can be used to reveal transformation tumors with higher probability to switch from low-grade gliomas to GB." (PMID 35454156, 2022).
KRT33B also shares sentences with these, for which no sentence is quoted: cancer (1 paper); glioblastoma (1); staphylococcus aureus infection (1); tumor (1).